RIPK2 (receptor interacting serine/threonine kinase 2)
Diseases named in the same sentence as RIPK2 in open-access papers (continued):
Sharing a sentence is not in itself a finding about the gene and the disease.
tumor (continued). "According to the expression level of RIPK2 in tumour tissues, RIPK2 was divided into high expression and low expression, and the correlation between different expression levels of RIPK2 and the prognosis of patients with different tumours was investigated." (PMID 35473583, 2022). "Through the immunofluorescence staining, we found that the expression level of RIPK2 protein in the tumor tissue was higher than the normal tissue in KIRC." (PMID 35508972, 2022). "In KIRC, the expression of RIPK2 was negatively related to tumor purity (r = − 0.21, p < 0.001), B cell (r = 0.35, p < 0.001), macrophage (r = 0.30, p < 0.001), and neutrophil (r = 0.46, p < 0.001)." (PMID 35508972, 2022). "We analysed these tumours and found that RIPK2 expression was higher in DLBC, LGG and OV than in normal tissues (P < 0.05)." (PMID 35473583, 2022). "Our analysis demonstrated that RIPK2 upregulation correlated with signature genes of tumor immunity, clinical features of metastasis, and high histological grade, suggesting that RIPK is a potential oncogene and unfavorable clinical prognosis marker for KIRC." (PMID 33790054, 2021). "RIPK2 was differentially expressed in tumor tissues compared to that in the adjacent normal tissues." (PMID 33633788, 2021). "Since the RIPK2 gene was aberrantly upregulated in KIRC tumor samples, we next determined the prognostic value of its expression in KIRC patients." (PMID 33790054, 2021). "And the positive correlation between ITGA5, NOD2, P2RX4, RIPK2, SLC7A1 and immune score indicated that the tumor tissue in the high-risk group is highly infiltrated by immune cells, which is consistent with risk score." (PMID 33828988, 2021). "Previous studies have reported that the gene RIPK2 played important roles in both inflammatory activity and tumor invasion and metastasis processes." (PMID 33790054, 2021). "The over-expression trend of RIPK2 was also detected when compared with the matched tumor samples with adjacent normal samples (P < 0.0001) (bottom, linear-scale)." (PMID 33790054, 2021). "The results showed that the RIPK2 gene was dramatically higher expressed in KIRC tumor samples (N = 526) compared with normal tissues (N=72) (top, log-scale)." (PMID 33790054, 2021). "Collectively, these data demonstrated an obvious positive correlation between dysregulation of RIPK2 gene expression and immunological changes in the tumor microenvironment." (PMID 33790054, 2021). "We observed that, the tumor size of nude mice in the RIPK2-knockdown group was significantly smaller, suggesting that inhibition of RIPK2 activity effectively suppress tumor growth in vivo." (PMID 33790054, 2021). "The genomics, transcriptomics, and clinical data of the KIRC cohort (a total of 526 tumor samples) from the TCGA database were been explored to obtain a better understanding of the roles of the RIPK2 gene in the carcinogenesis process of KIRC." (PMID 33790054, 2021). "Surprisingly, RIPK2 activity was elevated in the pre-neoadjuvant chemotherapy tumor tissues when compared to normal (p-value = 0.006) and immunohistochemical staining was significantly elevated in matched post-chemotherapy tissue (p-value < 0.0001)." (PMID 29874851, 2018). "Finally, we validated the role of the RIPK2/P-gp signaling pathway in DTX resistance using xenograft tumor experiments." (PMID 41563982, 2026). "RIPK2 is involved in tumor cell proliferation, migration, invasion, and metastasis." (PMID 41563982, 2026). "The findings indicated a negative association between RIPK2 expression and tumor stemness in PCPG, LGG, LUSC, LIHC, KIRC and HNSC, while a positive correlation was observed in other contexts." (PMID 38164277, 2024). "It was indicated that the expression of PCNA was lower in RIPK2-silenced group tumor section, which suggested that knockdown of RIPK2 might inhibit GC cells growth by affecting PCNA." (PMID 38164277, 2024). "NOD2 and RIPK2 were expressed differentially by tumor and normal or adjacent normal tissue." (PMID 38742117, 2024).
tumor (continued). "In this study, we conducted a preliminary analysis of the role of four RIPK family genes in tumors, with a specific focus on examining the correlation between RIPK2 and tumor immune cell infiltration, immune-related biomarkers, tumor heterogeneity, and tumor stemness in GC." (PMID 38164277, 2024). "To investigate the effects of RIPK2 on tumor cells growth, we choose GC cells to demonstrate it." (PMID 38164277, 2024). "As expected, the tumor weight and volume of sh-RIPK2 group were lighter and smaller than NC group." (PMID 38164277, 2024). "Also, RIPK2 has shown overexpression in tumour tissues, triggering cytotoxic T lymphocyte dysfunction." (PMID 39232464, 2024). "Finally, in vivo experiments provided further validation of the inhibitory effect of RIPK2 on GC tumor growth." (PMID 38164277, 2024). "Consequently, these results suggest that RIPK2 shows promise as a potential target for tumor immunotherapy in GC; however, further confirmation is necessary." (PMID 38164277, 2024). "On the other hand, NODs and RIPK2 in the early stage can activate the adaptive immune response, thereby killing tumor cells; however, overactivated such proteins may be the prime mover behind aggravated inflammation and tumor progression in the advanced stage." (PMID 37324457, 2023). "Regarding the application of RIPK2 inhibitors in tumor therapy, we hold the opinion that three main aspects could be considered." (PMID 37324457, 2023). "Observing the apparent influence of RIPK2 expression on the malignant phenotypes in vitro, the in vivo studies were then performed to test whether RIPK2 knockout could inhibit tumor growth and liver metastasis." (PMID 37016317, 2023). "Deletion of RIPK2 inhibits tumor growth and limits the formation of liver metastatic foci." (PMID 37016317, 2023). "Therefore, the effectiveness of RIPK2 as an anti-tumor target has been comprehensively verified, and the specific-targeting feasibility of RIPK2 will be further discussed in the following part." (PMID 37324457, 2023). "This means that precise differentiation and staging of tumors with the indicated phenotype, like excessive activation of NF-κB, has important reference value for the application of RIPK2 inhibitors as anti-tumor drugs or biological modulators enhancing the effectiveness of antineoplastic agents." (PMID 37324457, 2023). "The GO enrichment analysis results suggested that the mechanism of RIPK2 in tumours may involve I-kappaB kinase/NF-kappaB signalling, ribonucleoprotein granule and ubiquitin-like protein ligase binding." (PMID 35473583, 2022). "Independent cohorts were utilized to explore the role of RIPK2 in tumor immunotherapy response." (PMID 35508972, 2022). "All these data suggested that RIPK2 was closely related to tumor immune infiltration." (PMID 35508972, 2022). "According to KEGG analysis, RIPK2 may play a role in tumours mainly through the NOD-like signalling pathway and NF-Kappa B signalling pathway." (PMID 35473583, 2022). "RIPK2 was mainly moderately expressed in other tumour tissues." (PMID 35473583, 2022). "High expression of RIPK2 promotes the occurrence and development of tumours." (PMID 35473583, 2022). "RIPK2 expression was related to tumor microenvironment alterations, which might participate in the formation of Taxol resistance." (PMID 35477477, 2022). "Moreover, the relationship between RIPK2 expression and tumor pathological stages was explored, and the results showed that the expression of RIPK2 was significantly correlated with pathological stages." (PMID 35508972, 2022). "Therefore, we analysed RIPK2 in 33 different tumours through data from the TCGA, GTEx, HPA, CPTAC, GEPIA2 and other databases or websites." (PMID 35473583, 2022). "According to the KEGG analysis, RIPK2 may play a role in tumour mainly through NOD-like signaling pathway and NF-kappaB signaling pathway." (PMID 35473583, 2022).
tumor (continued). "Taken together, a positive correlation between gene copy number amplification and over-expression of the gene RIPK2 was observed in KIRC tumor samples, and its up-regulated expression could serve as an adverse prognostic marker for KIRC patients." (PMID 33790054, 2021). "Interestingly, a strong correlation between RIPK2 over-expression and dysregulated tumor immune infiltration level was found in this work." (PMID 33790054, 2021). "A recent study also elucidated that, by targeting TRAF6 in intestinal epithelial cells (IECs) and Receptor Interacting Serine/Threonine Kinase 2 (RIPK2) within the myeloid cells, miR-146a can keep IL-17 signaling in check, repressing inflammation further and suppressing tumor growth." (PMID 34571853, 2021). "Moreover, we also observed that there were dramatic differences in tumor stage and histologic grade distribution between high- and low-expression of RIPK2 sub-groups." (PMID 33790054, 2021). "As expected, the tumor samples with metastasis status: M1 (spread to other parts of the body patients) were dramatically enriched in the sub-groups of KIRC patients harboring high-expression of the RIPK2 gene (P < 0.0001)." (PMID 33790054, 2021). "Our result showed that RIPK2 was upregulated in KIRC tumor samples compared with normal samples." (PMID 33790054, 2021). "Therefore, further studies identifying RIPK2 as a prognostic factor and tumor marker in CRC entails a potential hope for CRC targeted therapy." (PMID 34356990, 2021). "In addition, RIPK2 may play a role in tumor immune escape by inhibiting antigen presentation and the cytotoxicity of cytotoxic T cells." (PMID 41563982, 2026). "Furthermore, deletion of receptor‐interacting protein kinase 2 (RIPK2), a key regulator of the tumour microenvironment, disrupts NBR1‐mediated degradation and further augments MHC‐I surface expression, ultimately sensitizing PDAC tumours to anti–PD‐1 immunotherapy." (PMID 40673641, 2025). "Consequently, the relationship between RIPK2 expression and tumor stemness was investigated." (PMID 38164277, 2024). "RIPK2 knockout could inhibit subcutaneous tumor growth and liver metastasis of PC." (PMID 37016317, 2023). "Furthermore, we can observe a positive correlation between active RIPK2 (as monitored by RIPK2 pY474 antibody) and methylation status of RASSF1A in IBC tumor samples, to suggest expression loss of RASSF1A with increased levels of RASSF1A CpG methylation, and increased activation of active RIPK2." (PMID 36983040, 2023). "In addition, to determine whether RIPK2-KO affects tumor growth in vivo, we performed a subcutaneous injection of control and RIPK2-KO 22Rv1 cells in male SCID/Beige mice." (PMID 35115556, 2022). "In addition, RIPK2 also plays an important role in the tumour microenvironment." (PMID 35473583, 2022). "Interestingly, immunotherapy responder’s monocyte/macrophage had the higher expression of RIPK2 than non-responder, which indicated that RIPK2 was associated with tumor immune suppressive cells and immunotherapy resistance." (PMID 35508972, 2022). "Notably, higher methylation levels of RIPK2 were also found in tumor tissues." (PMID 35907206, 2022). "Furthermore, to investigate whether some specific subsets of leukocytes were affected by the RIPK2 expression level, we estimated the abundance of each immune cell phenotype in the tumor microenvironment of KIRC by using the TIMER algorithm." (PMID 33790054, 2021). "Therefore, loss of RASSF1A in IBC may be an interesting marker for increased inflammation via hyperactive RIPK2 and increased growth (via reduced tumor suppression due to increased methylation of RASSF1A) in IBC." (PMID 29874851, 2018). "We further validated the role of the RIPK2/NF-κB/P-gp pathway in DTX resistance using in vitro cellular experiments and xenograft tumor experiments." (PMID 41563982, 2026).
tumor (continued). "Furthermore, TUNEL assay was performed to detect the apoptosis cells in both two groups' tumor section, and it was shown that the quantification of red fluorescent intensity in RIPK2-silenced group is higher, which demonstrated that knockdown of RIPK2 promotes the GC cell apoptosis in vivo." (PMID 38164277, 2024). "A comprehensive search on PubMed revealed a growing number of articles investigating RIPK family genes, particularly RIPK1, RIPK2, RIPK3 and RIPK4, in the context of tumor research." (PMID 38164277, 2024). "In the present study, we also observed a correlation between RIPK2 and immune checkpoint inhibitors immunotherapy-related biomarkers, including TMB, MSI, and tumor stemness." (PMID 38164277, 2024). "It was also revealed that RIPK2 expression was correlated to immunotherapy response biomarkers, namely MSI and TMB, and tumor stemness." (PMID 38164277, 2024). "Given the high rate of GBM tumor relapse and therapeutic resistance, the observed sensitivity of GBM CSCs to RIPK2-induced apoptosis has profound implications for the development of new therapies for GBM." (PMID 37324457, 2023). "Both the expression of RIPK2 and PRKCI in tumor tissues decreased in mice of the RIPK2KO group than mice of the RIPK2Scramble group." (PMID 37016317, 2023). "RIPK2 was highly expressed in most tumours (such as BRCA, COAD and LUSC, etc.), and the high expression of RIPK2 was correlated with tumour stage and prognosis." (PMID 35473583, 2022). "Further, the RIPK2 expression of metastatic PRAD, BRCA, KIRC, ESCA, and PAAD tumor was significantly higher than primary tumor." (PMID 35508972, 2022). "Our findings identified RIPK2 as a potential oncogenic gene for KIRC and revealed its involvement in dysregulated immunological activities in the tumor microenvironment of KIRC." (PMID 33790054, 2021). "We were able to obtain eight tumor matched tissues of the same IBC patients at diagnosis and post-neoadjuvant chemotherapy and immmunohistochemically stained them with a RIPK2 phospho-Y474 antibody as a surrogate marker for active RIPK2." (PMID 29874851, 2018). "We can observe a positive correlation between RIPK2 activity and methylation status of RASSF1A in IBC tumor samples." (PMID 29874851, 2018). "Another hypothesis involves the tumor suppressor RASSF1A, which, when hypermethylated, results in reduced expression, weakening the inhibition of NOD2/RIPK2 signaling in IBC." (PMID 40406369, 2025). "In vitro and in vivo experiments confirmed that RIPK2 specifically promotes tumor cell migration and invasion, rather than proliferation." (PMID 40185717, 2025). "Therefore, this makes sense to choose RIPK2 as a candidate target for OC, as RIPK2 inhibitors could be used in combination with chemotherapy agents to grapple with potential drug resistance and significantly ameliorate the original immune microenvironment that promotes tumor progression." (PMID 37324457, 2023). "Collectively, the results suggest that RIPK2 is mainly required for PC metastasis rather than tumor growth." (PMID 35115556, 2022). "RAD21, BOP1, POLR2E, and PRKDC were mainly expressed in tumor cells, RIPK2 was mainly expressed in monocytes, MAP2K2 was mainly expressed in tumor cells and macrophages, NBN was mainly expressed in macrophages and monocytes, and GPX4 was mainly expressed in tumor cells and T cells." (PMID 36212155, 2022). "RIPK2 promoted various immunological signaling pathways and immune phenotypes (including CD8 T cell, Dendritic cell, B cells, Neutrophils, and Macrophages) in the tumor microenvironment." (PMID 33790054, 2021). "However, a comprehensive pancancer analysis between RIPK2 and various tumour types has not been reported." (PMID 35473583, 2022). "To evaluate whether RIPK2 can be used as a potential therapeutic target in KIRC, we established the xenograft model by injection of RIPK2-knockdown or control cells into nude mice and monitored the tumor size over time." (PMID 33790054, 2021).
tumor (continued). "Furthermore, RIPK2 has not been reported as a tumour suppressor gene." (PMID 35473583, 2022). "Thus, we sought to not only confirm the differential expression of RIPK2, FOXQ1, KRT23 and EPHX4 in the investigated tumor samples, but also examine whether the differential epigenetic marking of the genes was, indeed, specific for tumor cells and not from stromal contamination." (PMID 31404997, 2019).